NOTCH4 (notch receptor 4)
Diseases named in the same sentence as NOTCH4 in open-access papers (continued):
Sharing a sentence is not in itself a finding about the gene and the disease.
breast cancer (continued). "In mice, NOTCH4 activation in the ductal epithelium required RBPjκ for physiological alveolar development, but not for breast cancer development, suggesting Notch4 functions via both canonical and non-canonical pathway in the breast endothelium." (PMID 34665379, 2022). "Additionally, the treatment with an FK506-binding protein-like (FKBPL)-based peptide repressed a subpopulation of endocrine therapy-resistant CSC in ER+ breast cancer by interfering with DLL4 and Notch4 signaling." (PMID 34680255, 2021). "Of note, although growing evidence indicated the selective targeting of Notch4 of therapeutic relevance in certain tumors, including the ER+ metastatic hormone-refractory breast cancer, no Notch4-blocking antibodies are under clinical investigation." (PMID 34680255, 2021). "Knockdown of TACC3 upregulates the expression of Notch4 and CDH5, suggesting that TACC3 may be closely related to Notch4 and CDH5 signaling pathways in breast cancer." (PMID 34149795, 2021). "In cells immune-stained for endogenous Notch4, protein was detected in the nucleolus and nucleoplasm, which was also confirmed by the co-localization of NIC4-GFP with RFP-tagged nucleolar proteins in breast cancer cells or the unrelated HEK cell line." (PMID 32123583, 2020). "Breast cancer cells expressed Notch1 and Notch4 proteins at variable steady-state levels regardless of the ER status." (PMID 32636747, 2020). "Notch genes (Notch1 and Notch4), when expressed under the control of whey acidic protein (WAP) or mouse mammary tumor virus (MMTV) promoters in the mouse, result in the formation of mammary carcinoma." (PMID 32391382, 2020). "In particular, Kim and colleagues revealed that treatment of MCF-7, MDA-MB-231, and SUM159 human breast cancer cells with Benzyl isothiocyanate (BITC), a constituent of cruciferous vegetables, increases levels of the active form of Notch1, Notch2, and Notch4 in both cultured and xenografted cells." (PMID 31379945, 2019). "Both Notch1 and Notch4 are found to have differential activities in breast cancer cell lines and patient samples, with Notch4 being the major receptor in the CSC populations of luminal and basal breast cancer cell lines." (PMID 30061899, 2018). "In breast cancer stem cells, high levels of prolyl-isomerase Pin1 sustain Notch signaling protecting Notch1 and Notch4 from proteasomal degradation." (PMID 30478302, 2018). "The relevance of the non-canonical-Notch/NF-κB/IL-6 axis stems from the evidence that, while canonical Notch4 is necessary for the development of mammary glands, non-canonical Notch4 signaling is related to breast cancer tumorigenesis." (PMID 30154786, 2018). "NOTCH1 and NOTCH4 pro-viral integration sites mediate mammary tumour formation, Notch4 is upregulated in T-ISC in primary non-invasive and invasive ER positive breast cancers and Notch1 overexpression in breast cancer correlates with worse prognosis." (PMID 23982961, 2013). "In addition, in breast cancer, NOTCH1 and NOTCH4 have been positively correlated with stemness, and blocking antibodies to NOTCH4 reduces mammosphere formation." (PMID 22225988, 2012). "Therefore, they do not identify Notch4 as a potential therapeutic target in this subtype of breast cancer." (PMID 41463075, 2025). "Notch 4’s role in breast cancer is not well-defined compared to other Notch receptors, but has been linked to angiogenesis and vascularization, which may influence tumour growth and metastasis." (PMID 37726449, 2024). "NOTCH4 is activated binding to its corresponding ligand to participate in the NOTCH pathway, closely involving in regulating the EMT process and promoting the invasion and metastasis of colorectal cancer, breast cancer, melanoma, lung adenocarcinoma and other cancers." (PMID 39309008, 2024).
breast cancer (continued). "Although higher expression of Notch4 mRNA is seemingly associated with poorer OS and RFS in breast cancer and TNBC patients without lymph node metastasis, lower expression of Notch4 mRNA is seemingly correlated with poorer OS and RFS in breast cancer and TNBC patients with lymph node metastasis." (PMID 37149651, 2023). "In addition, transcription of Notch1 and Notch4 is activated by ETV4 in breast cancer cells, suggesting the involvement of ETV4 in stimulating Notch signaling." (PMID 34052833, 2021). "Ablation of Notch4 but not Notch1 in the breast cancer cell lines MDA-MB-231 and Hs578T modulated sensitivity to genotoxic stress, which agreed with outcomes of overexpressing NIC4 and its role in modulating signaling cascades that confer protection from genomic damage." (PMID 32123583, 2020). "Harrison and coworkers isolated BCSCs from breast cancer cell lines and primary breast cancer samples by sorting cells resistant to anoikis or cells containing markers of ESA+/CD44+/CD24low, and they found that Notch4 is specifically overexpressed in these BCSCs." (PMID 29069872, 2017). "Interestingly, Notch4 was first discovered as an integration site for MMTV, previously termed Int3, which resulted in the constitutive expression of a cleaved form of Int3/NICD4, which drives the formation of mammary tumors." (PMID 25080108, 2014). "However, EMT does not occur in mammary tumors of mice transgenic for Tgfa, Neu, Notch4, and Wnt1, which indicates that the morphologic features associated with cancer progression are determined by the initiating oncogenic events." (PMID 15535849, 2004). "Orthotopic transplantation of mammary tumor cells is a well-established model for in vivo studies of breast tumorigenesis, and we chose this approach because it allowed us to study host Notch4-mediated effects on tumorigenesis independent of Notch4 activity in the tumor cell compartment." (PMID 23601498, 2013). "Based on previous research and our results, we found that Notch4 was expressed predominantly in TNBC cell lines MDA-MB-231 and Hs578T but not in luminal breast cancer cell lines MCF-7 and T47D." (PMID 37149651, 2023). "In relation to Notch 4, four distinct Akt phosphorylation binding sites within Notch 4 ICD were identified in breast cancer in vitro and in vivo models." (PMID 32575680, 2020). "Although a direct link with notch-4 has not been described, GPER has been shown to engage notch-1 signaling to alter gene expression and cell migration in breast cancer in vitro." (PMID 29899833, 2018). "Jagged1-mediated Notch signaling activation was able to activate the EMT process and increase migration and invasion in breast cancer mainly though upregulation of N1ICD, rather than Notch2 NICD (N2ICD), Notch3 NICD (N3ICD), or Notch4 NICD (N4ICD)." (PMID 25645291, 2015). "Here we show that NILCO components (Notch1, Notch4, JAG1, DLL4, leptin, OB-R, IL-1R tI) and target molecules (VEGF and VEGFR2) were co-expressed in breast cancer tissues, irrespective of ER, PR and, HER2 statuses." (PMID 24716804, 2014). "Continuous A_HSCORE (positive or negative) of Notch1, Notch4, JAG1, OB-R, VEGF and, VEGFR2 were not significantly different among breast cancers irrespective of their expression of ER, HER2 and PR." (PMID 24716804, 2014).
schizophrenia (32 papers, 2009 to 2025). A major psychotic disorder characterized by abnormalities in the perception or expression of reality. "Specifically, these associations included many HLA gene variants and also the NOTCH4 gene which has been associated with schizophrenia, psoriasis and asthma." (PMID 40349045, 2025). "Wei and Hemmings found that the NOTCH4 locus was involved in susceptibility to schizophrenia in a British population." (PMID 32646407, 2020). "Fourth, previous studies confirmed the relationship between schizophrenia and NOTCH4 polymorphisms, including single nucleotide polymorphisms (SNPs) (e.g., rs520692, rs3131296, rs204993, and rs2071287)." (PMID 32646407, 2020). "Previous studies have reported that NOTCH4 polymorphism of rs204993 is closely related to schizophrenia." (PMID 32646407, 2020). "NOTCH4, another gene that maps to the HLA locus, has been implicated as a schizophrenia risk gene in various studies." (PMID 31642026, 2020). "The relationship between schizophrenia and the common variants of NOTCH4 gene was also found among different racial populations (the rs2071287 and rs3131296 in European and Japanese population)." (PMID 32646407, 2020). "In the present study, we found an aberrant functional connectivity in the left occipital cortex among carriers with the NOTCH4 rs204993 schizophrenia-risk genotypes." (PMID 32646407, 2020). "Recently, a study among 218 Taiwanese families reported another SNP, rs204993 with a significant relationship with schizophrenia, found by testing the association of the entire genomic region of NOTCH4." (PMID 32646407, 2020). "Multiple genetic association studies have associated NOTCH4 with schizophrenia and rheumatoid arthritis, but their functional implications are uncertain." (PMID 28560257, 2017). "Several diseases have reported associations either within or in the vicinity of NOTCH4, most extensively schizophrenia." (PMID 25521205, 2014). "A variant in Notch4 has been associated with schizophrenia, and recent analyses suggested that polymorphisms affecting the alternative splicing of Notch4 may increase schizophrenia susceptibility." (PMID 36237531, 2022). "A common variant in the NOTCH4 gene, rs204993, has been linked with schizophrenia, but the neural underpinnings are largely unknown." (PMID 32646407, 2020). "Moreover, NOTCH4 has been associated with some cognitive endophenotypes of schizophrenia, and also with some frontal lobe structural variations between patients and controls." (PMID 28180029, 2016). "The NOTCH4 gene has also been identified as a possible susceptibility gene for schizophrenia (SCZ)." (PMID 26605328, 2015). "Meanwhile, the Notch4 locus has been identified as a candidate susceptibility gene for schizophrenia, and the mRNA level of Notch1 is differentially expressed in parvalbumin-immunoreactive neurons in subjects with schizophrenia." (PMID 26232790, 2015). "NOTCH4 gene mutation may be associated with migraine and schizophrenia." (PMID 35783123, 2022). "Two different significant SNPs (rs3131296 and rs2071287) map closely to the gene NOTCH4 (neurogenic locus notch homolog 4), which codes for a transmembrane protein critical for neurodevelopmental processes; NOTCH4 has been implicated as a schizophrenia risk gene in other studies." (PMID 28180029, 2016). "Finally, mutations in the Notch4 gene may be associated with schizophrenia." (PMID 38790158, 2024). "False‐positive report probability values for the association between NOTCH4 rs2071287, NOTCH4 rs204993, and CYP2E1 rs2070673 and the risk of schizophrenia." (PMID 39698532, 2024). "In the current study, we aimed to investigate the genetic effect of the schizophrenia-related gene (NOTCH4 rs204993 genotype) on brain function and its relationship with schizotypal traits among healthy volunteers." (PMID 32646407, 2020).
schizophrenia (continued). "In present study, we aimed to investigate the genetic effect of the schizophrenia-related gene (NOTCH4 rs204993 genotype) on brain function and its relationship with schizotypal traits among healthy volunteers." (PMID 32646407, 2020). "Therefore, the NOTCH4 gene variants may potentially affect the function or expression level of the Notch4 protein, which in turn influences the neurodevelopment of certain psychiatric disorders, such as schizophrenia and schizotypal traits." (PMID 32646407, 2020). "For example, rs3131296 is located in the largest intron (intron 18) of the neurogenic locus notch homolog protein 4 (NOTCH4), which is one of the top candidate genes for schizophrenia." (PMID 30924326, 2019). "NOTCH4 has been the subject of many studies of schizophrenia." (PMID 36509785, 2022). "In addition, variants in CACNA1C, NOTCH4 and COMT had been reported to be associated with schizophrenia in GWAS studies." (PMID 32273551, 2020). "Interaction between COMT (elite gene) and NOTCH4 genotypes may predict the treatment response to typical neuroleptics in schizophrenia patients." (PMID 30705251, 2019). "There are conflicting reports about the linkage of NOTCH4 variants to neurological conditions including schizophrenia and Alzheimer’s disease but none linking it to PD56–59." (PMID 30833663, 2019). "OMIM recorded that NOTCH4 was highly related to schizophrenia." (PMID 26253105, 2015). "However, the effect of the common variant of the NOTCH4 gene, SNP rs204993, on brain function and its relationship with schizophrenia trait has not been investigated." (PMID 32646407, 2020). "However, meta-analysis of the Japanese samples with 479 cases and 2938 controls from a United Kingdom (UK) schizophrenia GWAS showed that the SULT6B1 SNP (p = 3.7 × 10−5) as well as SNPs in the GIRK2 (rs2787566, p = 0.0014) and NOTCH4 (rs2071287, p = 0.0014) genes were associated with schizophrenia." (PMID 28855529, 2017). "Finally, two CpGs presently identified to be differentially methylated in anxiety disorders map to the Neurogenic Locus Notch Homolog Protein 4 (NOTCH4) gene, which has been identified as a risk factor in schizophrenia, but has not been implicated in anxiety-related phenotypes before." (PMID 40281224, 2025). "A meta-analysis of 18 GWASs for schizophrenia supported involvement of the MHC region, TCF4, POM121L2, NOTCH4, AS3MT, CNNM2, and NT5C2." (PMID 27064909, 2016). "NOTCH4 is a non-HLA gene that maps to the HLA locus, suggesting that that both immune and non-immune functions of genes in the HLA locus may be involved in the pathogenesis of schizophrenia." (PMID 28180029, 2016). "This analysis revealed top genes, such as NOTCH4, MICA, TRIM27, PBX2, and FKBPL, as enriched in GWAS of schizophrenia, CLZ-induced agranulocytosis/granulocytopenia in treatment-resistant schizophrenia, and bipolar disorder among other psychiatric and non-psychiatric conditions." (PMID 35664466, 2022).
melanoma (25 papers, 2016 to 2025). A malignant, usually aggressive tumor composed of atypical, neoplastic melanocytes. "In NRAS wildtype melanoma, NOTCH4 mutation was suggested as a biomarker that predicts good immune response." (PMID 36672468, 2023). "In this context it is noteworthy that a recent report implicated NOTCH4 as a tumor suppressor in melanoma." (PMID 36672468, 2023). "A total of 189 NRAS wildtype melanoma were enrolled in the validation cohort, and the NOTCH4 mutation frequency in the validation cohort was 12% (22/189)." (PMID 35967450, 2022). "NRAS wildtype melanomas with NOTCH4-Mut were identified to be associated with prolonged overall survival (OS) in both the discovery (HR: 0.30, 95% CI: 0.11–0.83, P = 0.01) and validation cohorts(HR: 0.21, 95% CI: 0.07–0.68, P = 0.003)." (PMID 35967450, 2022). "It is known that Notch-4 is deeply implicated in cancer development and can be a clinically significant marker of melanoma stem cell function." (PMID 34337053, 2021). "Recent studies have indicated that Notch4 mutations may serve as predictive biomarkers for melanoma immunotherapy." (PMID 39897423, 2025). "Additionally, we elucidated for the first time the relevance of NOTCH4 mutations to the DDR pathway in melanoma." (PMID 35967450, 2022). "The percentage of NOTCH4 mutations is 9.4% (9/96) in NRAS wildtype melanoma." (PMID 35967450, 2022). "Therefore, we used the DDR gene sets from MSigDB to explore the differences in DDR pathway mutations between NOTCH4-Mut and NOTCH4-Wt tumors in NRAS-wildtype melanoma." (PMID 35967450, 2022). "Additionally, the overall mutation frequency of NOTCH4 was 2.96% (324/10,953) in the TCGA pan-cancer cohort, with melanoma at 15.61% (69/442) ranking first." (PMID 35967450, 2022). "In that study, the NOTCH4 mutation had a predictive value of melanoma in the discovery cohort." (PMID 35967450, 2022). "For example, NOTCH4 mutations promote the metastasis of melanoma cells." (PMID 34158601, 2021). "Consequently, more DDR pathway mutations in NOTCH4-Mut melanoma may be a reason why immunotherapies are more effective in these patients." (PMID 35967450, 2022). "DLL4 was identified as ligand of Notch1 in hepatocellular carcinoma, Notch4 in glioblastoma and Notch3 in melanoma." (PMID 39951484, 2025). "Nevertheless, others have reported that high Notch4 expression enhances the expression of E-cadherin and attenuates melanoma malignant behaviour." (PMID 37108670, 2023). "In melanoma and head and neck squamous cell carcinoma, Notch4 signalling induces EMT by stimulating the expression of EMT markers such as Vimentin and Twist1 and downregulating the expression of E-cadherin." (PMID 37108670, 2023). "In NRAS mutant patients of the validation cohort, NOTCH4 wildtype melanoma had longer OS (mOS: 31.3 months vs. 22.6 months, HR = 1.23, 95% CI: 0.48–3.18, P = 0.68) than NOTCH4-Mut patients." (PMID 35967450, 2022). "In summary, our study indicates the favorable relationship between NOTCH4 mutation and better clinical outcomes in ICI treatment NRAS wildtype melanoma patients." (PMID 35967450, 2022). "For examples, in melanoma, Notch4 interacts with CSCs expressing CD133 and ABCG2 and this promotes CSCs to form melanoma." (PMID 35903544, 2022). "Actually, we also performed additional analysis of NOTCH4 predictive value within NRAS mutant melanoma both in the discovery and validation cohorts." (PMID 35967450, 2022). "In particular, Notch4 was found to induce VM in melanoma cells in a Nodal-dependent way since the treatment with recombinant human Nodal was able to rescue VM ability impaired by Notch4 inhibition." (PMID 36224457, 2022). "In our research, we comprehensively converged and consolidated both genomic and clinical data to evaluate the relationship between NOTCH4 mutation and the outcome of an ICI-treated NRAS wildtype melanoma cohort." (PMID 35967450, 2022).